SLFN11 (schlafen family member 11)
Diseases named in the same sentence as SLFN11 in open-access papers (continued):
Sharing a sentence is not in itself a finding about the gene and the disease.
tumor (continued). "The results demonstrated that SLFN5, SLFN11, SLFN12, SLFN12L, and SLFN13 expression in tumor tissues was significantly higher than that in normal tissues in paired, and unpaired tests, implying that they may play a role in promoting tumor progression in GC." (PMID 36090985, 2022). "The median value of SLFN11 positivity was 15%; hence, we defined a positive result as ≥15% of the tumor nuclei stained, regardless of the intensity." (PMID 36741698, 2022). "Lack of SLFN11 expression makes the functionality of the SLFN11-mediated system impossible and increases tumor viability." (PMID 35625957, 2022). "SLFN11 protein expression varied across 13 different tumour types assessed by multi-tumour TMAs; 37% of all tumours tested showed no SLFN11." (PMID 34663950, 2021). "In support of this, recent work from our group in HGSOC patients demonstrated efficacy of the Wee1 inhibitor adavosertib in combination with gemcitabine, independent of tumour SLFN11 status (NCT02151292)." (PMID 34663950, 2021). "We, therefore, aimed to assess the presence of PARP1 and SLFN11 protein expression in clinically derived tumor tissue of UV AS and non-UV AS cases." (PMID 34085099, 2021). "Indeed, EZH2 levels are higher in SCLC than any other tumor type in TCGA, and EZH2 inhibitors can restore SLFN11 expression to potentially improve response to PARP inhibitors." (PMID 33578789, 2021). "Together, these findings indicated that low SLFN11 expression in HCC may manifest as poor prognosis and tumor aggressiveness." (PMID 32292519, 2020). "Expression of PARP1 and SLFN11 was assessed in 16 and 12 DSRCT tumor tissue samples, respectively." (PMID 32279088, 2020). "We found that SLFN11 expression was significantly downregulated in the tumor tissues of HCC compared with that expression in adjacent non-tumor tissues." (PMID 32292519, 2020). "The results revealed that SLFN11 was downregulated in 72.41% of tumor tissues (84/116) compared with nontumor liver tissues." (PMID 32292519, 2020). "PARP1 and SLFN11 expression was observed in 100% and 92% of DSRCT tumor tissues, respectively." (PMID 32279088, 2020). "The ACS-HN11 tumour model had the highest pimonidazole-positive hypoxic fraction as well as the highest MKI67, POR and SLFN11 expression, but was also p16-positive, thus an ~85–90% likelihood of being HPV-positive, and originated from a tumour that was recurrent post chemoradiotherapy." (PMID 31337055, 2019). "In cells with impaired IFNGR signaling, inactivation of SLFN11 did not influence sensitivity to T cells, indicating that SLFN11 exclusively operates by sensitizing tumor cells toward IFN-γ-mediated toxicity." (PMID 30753225, 2019). "Given that SLFN11 impairs DNA repair by inhibiting the translation of key DDR genes such as ATR, it is theoretically possible that tumor cells with low SLFN11 expression may be more dependent on residual ATR pathway activity for survival, making them particularly sensitive to ATR inhibitors." (PMID 40766331, 2025). "In addition to tumor cells, there are other non-tumor cells (such as immune cells) in tumor tissues, and SLFN11 is also expressed, or even strongly expressed, in these non-tumor cells." (PMID 40766331, 2025). "While increasing SLFN11 expression can be beneficial in many clinical cases, it may be the most beneficial in patients without any SLFN11 expression in the tumor." (PMID 38001424, 2023). "However, given that the intensity of SLFN11 expression was highly heterogeneous in some tumor tissues before CRT, it is possible that a population of cells with low SLFN11 expression in the primary tumors may have survived and proliferated after CRT." (PMID 36741698, 2022). "We have shown differences in the prevalence of sub-clonality across different tumour types, but our findings have not demonstrated that the presence of sub-clonality is determinate of response and instead that overall SLFN11 levels are more predictive of response to DDAs." (PMID 34663950, 2021).
tumor (continued). "Another tumor suppressor factor, Schlafen 11 (SLFN11), was also suggested to participate in drug resistance/sensitivity, and both ATM upregulation and SLFN11 downregulation can activate EMT to stimulate resistance of tumor cells to cisplatin-based chemotherapy." (PMID 34208465, 2021). "High levels of SLFN11 in SCLC compared to other tumour types might be related to the high levels of intratumoural heterogeneity and transcriptional plasticity observed in this tumour type." (PMID 34663950, 2021). "Notably, INK128 may effectively suppress tumor progression and metastasis of HCC in patients with low SLFN11 expression." (PMID 32292519, 2020). "We report the identification of Schlafen Family Member 11 (SLFN11) mRNA level as a biomarker predictive of response to chemotherapeutics, including topoisomerase inhibitors, alkylating agents, anti-metabolites, and anti-tumor anti-biotics in solid tumor lineages." (PMID 31682620, 2019). "To investigate the potential role of SLFN11 in HCC, we first examined its mRNA expression in paired tumor and nontumor liver tissues from 116 patients with HCC by qRT-PCR." (PMID 32292519, 2020). "To this end, we compared the expression of SLFN11 in paired tumor and nontumor liver tissues from HCC patients and analyzed the correlation between SLFN11 expression and survival rates." (PMID 32292519, 2020). "Although temolozomide and talazoparib alone had marginal anti-tumor activity in NCI-H209 and NCI-H841 xenografts models, the combination induced marked synergy in NCI-H209 (high SLFN11) but not in NCI-H841 (low SLFN11)." (PMID 27708213, 2016). "In a xenograft (PDX) model of triple-negative breast cancer (TNBC), the combination of irinotecan (TOP1 inhibitor) and ATR inhibitor VE-822 significantly improved tumor growth inhibition and inhibited CHK1 phosphorylation in SLFN11-negative tumors, overcoming the limitations of single-drug therapy." (PMID 40766331, 2025). "In addition, tumor samples of 96 non-UV AS patients were assessed for PARP1 and SLFN11 expression, showing 89–100% PARP1 positivity and 63–66% cases positive for SLFN11 expression." (PMID 34085099, 2021).
infection (4 papers, 2020 to 2025). The state of being infected such as from the introduction of a foreign agent such as serum, vaccine, antigenic substance or organism. "We previously reported that expression of several cellular genes, including CXADR, BNIP3, SPARCL1, SLFN11, BBS9 and BNIP3, is significantly downregulated by epigenetic means during the persistent phase of infection of B cells." (PMID 41497616, 2025). "After two months of infection, the number of viral genomes was determined and the relative level of mRNA for CXADR, BNIP3, SPARCL1 and SLFN11 was measured in infected and mock-infected cells." (PMID 41497616, 2025). "Considering that HCC in most patients in China and Asia is derived from infection of HBV, which is also a retrovirus, we sought to investigate the functions and pathways of SLFN11 in HCC." (PMID 32292519, 2020). "In addition, genes encoding, for example, APOBEC3 (apolipoprotein B mRNA editing enzyme catalytic polypeptide 3) family members, SLFN11, and SAMHD1 were enriched in CD3ko-Nef versus WT SIVmac239 infection." (PMID 32075764, 2020). "Furthermore, RL1 was necessary for down-regulation of SLFN11 in the context of infection, since neither a single-gene Merlin RL1-deletion mutant nor the RL1–RL6 block deletion recombinant was able to reduce SLFN11 levels." (PMID 35105802, 2022).
adenocarcinoma (3 papers, 2021 to 2023). A common cancer characterized by the presence of malignant glandular cells. "In addition to its predictive value of sensitivity, our data raise the hypothesis that SLFN11 expression may be a histologic biomarker to predict phenotypic transformation of adenocarcinoma into SCLC." (PMID 35511434, 2022).
SLFN11 also shares sentences with these, for which no sentence is quoted: acute myeloid leukemia (2 papers); head and neck cancer (2); serous carcinoma (2); B-cell acute lymphoblastic leukemia (1); B-cell chronic lymphocytic leukemia (1); B-cell lymphoma (1); bacterial infection (1); bladder urothelial carcinoma (1); Burkitt lymphoma (1); childhood asthma (1); chromophobe renal cell carcinoma (1); clear cell carcinoma (1); desmoplastic small round cell tumor (1); embryonal rhabdomyosarcoma (1); HIV-1 infection (1); infectious disease (1); laryngeal carcinoma (1); medulloblastoma (1); mental retardation (1); metabolic disorder (1); metastatic melanoma (1); metastatic prostate carcinoma (1); neurological disorders (1); oral cancer (1); ovarian endometrioid adenocarcinoma (1); papillary renal cell carcinoma (1); papillary thyroid carcinoma (1); plasma cell myeloma (1); small cell carcinoma (1); soft tissue sarcoma (1).
A further 1 disease shares a sentence with SLFN11 in 1 paper.